CCDC66 (coiled-coil domain containing 66)
Diseases named in the same sentence as CCDC66 in open-access papers (continued):
Sharing a sentence is not in itself a finding about the gene and the disease.
tumor (9 papers, 2017 to 2025). "The expression level of circ-CCDC66 was significantly associated with tumor size, TNM stage, and lymph node metastasis in patients with PTC." (PMID 35264065, 2022). "Circ-CCDC66 was significantly upregulated in tumor tissues compared with matched normal tissues.High expression of circ-CCDC-66 was found to associate with large tumor size and advanced tumor stage." (PMID 33407514, 2021). "circ-CCDC66 is upregulated in various tumor tissues and cells, such as cervical, papillary thyroid, and gastric cancers, and plays an important role in their pathogenesis." (PMID 40181128, 2025). "Another work described three other tumor genes (CCDC66, ZRANB2 and VCPKMT) for positive margin prediction based on gene expression signature." (PMID 38188288, 2023). "Circ-CCDC66 has been reported to be upregulated not only in renal cancer cell lines but also in tumor stem cell spheres, and enhances the enrichment of tumor stem cells." (PMID 35264065, 2022). "As cancer stem cells are responsible for the renal carcinoma cancer tumor growth and resistance to conventional therapy, we focus on the cir-CCDC66 influence on renal carcinoma cancer stem cells." (PMID 31994979, 2020). "All three makers were detected in most of the tumor fractions [cirRNA CCDC66 (82%, 9/11), FAK (82%, 9/11), and paxillin (91%, 10/11)]." (PMID 29855336, 2018). "The animal tumor model was used to assess the effect of circ-CCDC66 in vivo." (PMID 33407514, 2021). "In addition, cell proliferation, migration, and invasion involve many related pathways, and whether circ-CCDC66 can regulate the biological effects of tumor cells by regulating the expression of these pathways remains to be explored further." (PMID 35264065, 2022). "Moreover, downregulated circ-CCDC66 was found to suppress tumor growth in vivo." (PMID 33407514, 2021). "In papillary thyroid carcinoma, circ-CCDC66 upregulates LARP1 expression by binding to miR-129-5p, thereby enhancing cancer cell proliferation, migration, invasion, and transplanted tumor growth." (PMID 40181128, 2025). "CCDC66 is a member of the coiled-coil structural domain (CCDC) proteins, which act primarily as oncogenes to regulate tumor proliferation, metastasis, angiogenesis and apoptosis." (PMID 36624463, 2023). "After 25 days of cancer cell inoculation, the tumor growth volume and weight of nude mice injected with PTC cells transfected with LV-sh-circ-CCDC66 were significantly smaller than those of LV-sh-NC." (PMID 35264065, 2022). "In addition, we confirmed that inhibition of circ-CCDC66 could repress xenograft tumor growth." (PMID 35264065, 2022).
cancer (7 papers, 2018 to 2022). A tumor composed of atypical neoplastic, often pleomorphic cells that invade other tissues. "CircRNA coiled-coil domain containing 66 (circ-CCDC66) has been identified as a potential therapeutic target in cancer." (PMID 35264065, 2022). "Further mechanistic studies showed that hepatocyte growth factor/c-Met pathway was activated in cancer stem cell enrichment and responsible for the cir-CCDC66 upregulation." (PMID 31994979, 2020). "In our research, we detected the expression of cir-CCDC66 in several RCC cancer cell lines and found that cir-CCDC66 was with higher expression level in RCC cancers cell lines than normal renal cells." (PMID 31994979, 2020). "As the cir-CCDC66 is highly expressed in RCC cancer cells, we want to know the mechanism of abnormal expression of cir-CCDC66." (PMID 31994979, 2020). "In conclusion, our research revealed a novel mechanism between hepatocyte growth factor/c-Met/cir-CCDC66 and cancer stem cell enrichment." (PMID 31994979, 2020). "What’s more, the results showed that the RCC CSC spheres had high level of cir-CCDC66 expression than the RCC cancer cells suggesting that cir-CCDC66 was upregulated in CSCs." (PMID 31994979, 2020). "The results showed that cir-CCDC66 was upregulated not only in renal carcinoma cancer cancer cell lines but also in cancer stem cell spheres." (PMID 31994979, 2020). "In cancers, the circRNA CCDC66 has been shown to sponge miRNAs that target oncogenes, which promote cancer growth and metastasis." (PMID 30744636, 2019). "Showing that cirRNA CCDC66 was expressed in LADC cells, and its expression correlated with FAK, a marker that was associated with cancer metastasis, our results supported their findings." (PMID 29855336, 2018). "The results showed that cir-CCDC66 was upregulated in cancer cells." (PMID 31994979, 2020). "What’s more, the results showed that cir-CCDC66 enhanced the cancer stem cell enrichment." (PMID 31994979, 2020). "Interestingly, cirRNA CCDC66 was also detected in LADC cells, and its expression correlated with the levels of FAK mRNA, a vital marker closely associated with cancer metastasis and EMT." (PMID 29855336, 2018). "It has been reported that circ-CCDC66 is upregulated in colorectal cancer (CRC) cases and affects cancer development by mediating certain oncogenes." (PMID 35264065, 2022). "To figure out the function of cir-CCDC66 in CSCs enrichment, we knocked out cir-CCDC66 with transfection of cir-CCDC66 siRNAs and overexpressed cir-CCDC66 with transfection of plasmids in RCC cancer cell lines." (PMID 31994979, 2020).
retinopathies (2 papers, 2024 to 2025). "In this study, several candidate susceptibility genes including RP1L1, RPGR, RPE65 and CCDC66 were identified to be associated with CQ/HCQ retinopathy via exome sequencing and genome-wide association study." (PMID 38548946, 2024). "Several candidate susceptibility genes including RP1L1, RPGR, RPE65 and CCDC66 were identified to be associated with CQ/HCQ retinopathy." (PMID 38548946, 2024). "In GWAS analysis, we found 12 SNPs had a significant association (p < 10-4) with HCQ retinopathy in genes LCE4A, HRNR, OR2T4, NUDT17, CCDC66, PRSS3, PABPC1 and IGHV." (PMID 38548946, 2024). "Finally, our study highlights the need to expand research on CCDC66 mechanisms beyond retinal cells and documented retinopathies to include potential abnormalities in kidney development and other epithelial tissue defects." (PMID 40729374, 2025). "Exome sequencing revealed CCDC66 was present in 7 patients (24%, p7,9,12,25,31,35,37) with HCQ retinopathy and with a 38% higher difference of affected percentage." (PMID 38548946, 2024).
CCDC66 also shares sentences with these, for which no sentence is quoted: gastric cancer (2 papers); lung carcinoma (2); retinal ciliopathy (2); bladder cancer (1); gastrointestinal tumors (1); leukemia (1); liver cancer (1); oral cancer (1).